INS (insulin)
Diseases named in the same sentence as INS in open-access papers (continued):
Sharing a sentence is not in itself a finding about the gene and the disease.
type 1 diabetes (continued). "Type 1 diabetes (T1D) is a persistent autoimmune disorder where immune cells attack and destroy the insulin-producing beta cells of the pancreas." (PMID 34721424, 2021). "This is unexpected, since people with type 1 diabetes have typically managed with insulin dependency longer and all investigated complications were more common in the type 1 diabetes group also in early adulthood." (PMID 33475814, 2021). "flexible insulin therapy (FIT) is considered as a crucial turning point in the management of type 1 diabetes." (PMID 34909088, 2021). "This makes the body insulin dependent, and individuals diagnosed with type 1 diabetes take insulin injections daily." (PMID 34194606, 2021). "Among the main types of the disease, type 1 diabetes (T1D) is described to affect 5–10% of diagnosed cases, which is characterized by a widespread autoimmune destruction of insulin-secreting pancreatic β-cells." (PMID 34948265, 2021). "Type I Diabetes Mellitus relates to carbohydrate metabolism, as this disease’s predominant symptom is a decrease in the production of insulin." (PMID 33925648, 2021). "Type 1 diabetes (T1D) is considered as an autoimmune disease, where the insulin-producing β-cells are destroyed by immune attacks." (PMID 34884797, 2021). "Type 1 diabetes (T1D) is a chronic autoimmune disease arising from a targeted immune-mediated destruction of the insulin-producing β cells resided in the pancreatic islets of Langerhans." (PMID 34828301, 2021). "In our recent studies, macrosomic foetuses of mothers with type 1 diabetes had higher insulin, IR, and leptin levels." (PMID 34210228, 2021). "Type 1 diabetes is described as the inability of insulin production and secretion by pancreatic β-cells, resulting in autoimmune destruction." (PMID 34194606, 2021). "In 2019, the European Medicines Agency (EMA) approved a first SGLT-2i and a first dual SGLT-1/-2i to improve glycaemic control, as an adjunctive treatment to insulin in people with type 1 diabetes and a BMI ≥ 27 kg/m2." (PMID 34011313, 2021). "A novel dual-hormone closed-loop system delivering a fixed ratio of pramlintide:insulin was evaluated during a 24 h inpatient study in adults with type 1 diabetes." (PMID 33550442, 2021). "Type 1 diabetes (T1D) is an autoimmune disease characterized by the infiltration of inflammatory immune cells into pancreatic islets and progressive destruction of insulin-producing beta cells." (PMID 34621265, 2021). "Hybrid closed loop insulin delivery led to clinically significant reductions in hypoglycemia in adults with long standing type 1 diabetes complicated by hypoglycemia unawareness over 9 months." (PMID 33628834, 2021). "Type 1 diabetes is an autoimmune disease because of selective beta-cell destruction and insulin secretion defects." (PMID 34210228, 2021). "Because of the obesogenic effect of ghrelin and the fact that obesity in type 1 diabetes is frequently observed, we studied the relationship between ghrelin concentrations, BMI, metabolic control and insulin dosage." (PMID 34294136, 2021). "We have previously observed insulin-positive ductal cells in pancreas transplant biopsies where there is recurrent type 1 diabetes." (PMID 33912981, 2021). "In 20% (3/15) patients of type 1 diabetes insulin was discontinued, and 66.7% (8/12) patients, the daily insulin demand was reduced by more than 50% of the baseline." (PMID 33957998, 2021). "Due to the incomparability of studies and the low number of study participants, study findings were inconsistent regarding the role of dietary fat and protein for prandial insulin requirements in children with type 1 diabetes." (PMID 34684559, 2021). "In type 1 diabetes (T1D), pancreatic islets are targeted by finely programmed autoimmune responses, leading to selective demise of the insulin-producing β cells." (PMID 33822842, 2021). "Type 1 diabetes was diagnosed with autoantibodies against glutamic acid decarboxylase, tyrosine phosphatase and insulin." (PMID 34123705, 2021).
type 1 diabetes (continued). "In 2021, the 100th anniversary of the isolation of insulin and the rescue of a child with type 1 diabetes from death will be marked." (PMID 33494161, 2021). "Conversely, and consistent with the present study, acinar amylase content (expression and synthesis) is severely reduced in type-1 diabetic rat models (streptozotocin and alloxan), which is restored by insulin administration." (PMID 34282152, 2021). "Type 1 diabetes (T1D) is a chronic autoimmune disease leading to the complete destruction of insulin-producing beta cells." (PMID 34831471, 2021). "The destruction of insulin-producing β-cells is the main pathophysiological feature of type 1 diabetes (T1D)." (PMID 34202521, 2021). "Their effects are independent of insulin action, and blood glucose can therefore be reduced in patients with severe impairment of endogenous insulin production, even those with type 1 diabetes." (PMID 34768897, 2021). "Type 1 diabetes (T1D), also known as insulin-dependent diabetes, is a chronic autoimmune-mediated disease in which the insulin-producing pancreatic beta cells are destroyed." (PMID 34777313, 2021). "We next focus on selected compounds that have gained attention due to their potential benefits as adjuncts to insulin in type 1 diabetes." (PMID 33595677, 2021). "Type 1 diabetes requires a demanding and time-consuming treatment regimen that includes blood glucose monitoring, multiple insulin doses, carbohydrate counting and physical activity." (PMID 34356715, 2021). "Early introduction of insulin into the treatment of type 1 diabetes, in addition to the primary effect of good metabolic control, appears to have an additional effect on delaying the destruction of β-cells." (PMID 34959363, 2021). "Type 1 diabetes (T1D) self-management can be challenging, involving multiple daily injections of insulin (MDI) or continuous subcutaneous insulin infusion (CSII), guided by self-monitoring of glucose." (PMID 34283880, 2021). "Similar results were found in subjects with type 1 diabetes, in which insulin therapy inhibited protein breakdown." (PMID 34707570, 2021). "The FIT was adopted as a five-day inpatient training by a team from Dusseldorf to teach individuals with type 1 diabetes how to adapt their fast-acting insulin doses to their carbohydrate intakes and physical activity." (PMID 33585132, 2021). "This study focused on the use of automated cell-phone text messages (SMSs) sent as reminders about insulin injections to a patient population made up exclusively of adolescents with poorly controlled type 1 diabetes." (PMID 33720997, 2021). "The data consisted of measurements of plasma glucose, plasma insulin, and oxygen consumption collected from a study of 17 adults with type 1 diabetes undergoing aerobic exercise sessions." (PMID 33770092, 2021). "Human embryonic stem cells (hESCs) possess the ability to differentiate into insulin-producing cells (IPCs), which can be used to treat type I diabetes." (PMID 33897780, 2021). "Type 1 diabetes management is highly burdensome, requiring regular monitoring of blood glucose levels and careful insulin delivery." (PMID 33931977, 2021). "Future research should validate our findings by replicating the results in a larger sample of individuals with type 1 diabetes and studying the effects of implementing the prediction model in a closed-loop insulin delivery system." (PMID 34166426, 2021). "First, type 1 diabetes is always treated with insulin therapy (through injections or pump) and monitoring of glucose levels with a blood glucose meter or a continuous glucose monitoring system (CGM)." (PMID 36994341, 2021). "The primary goal of this study was to explore physical activity (PA) levels, hypoglycemia fear scores and hypoglycemia episodes according to insulin administration and blood glucose monitoring methods in youth with type 1 diabetes (T1D)." (PMID 34557162, 2021).
type 1 diabetes (continued). "In the case of type I diabetes, islet β-cells in the pancreas cannot produce enough insulin to metabolize glucose." (PMID 34287337, 2021). "The proportion of individuals with type 1 diabetes who are positive for EV protein in the pancreas is high (70–80%) and viral proteins are located mainly in insulin-positive cells." (PMID 34390364, 2021). "This patient had type 1 diabetes with a history of multiple insulin medications to manage the condition." (PMID 33824476, 2021). "Consistently, we herein detected a decreased cardiac OSTN expression in STZ-induced type 1 diabetes with lower insulin levels." (PMID 34135313, 2021). "All this contributes type 1 diabetes remission and by maintaining minimal insulin secretion, possibly postpones chronic complications." (PMID 34603200, 2021). "The earliest characterizations of patients with type 1 diabetes and animal models with surgical or chemical ablation of insulin-producing cells observed life-threatening ketosis." (PMID 34717951, 2021). "Type 1 Diabetes (T1D) is a health condition in which insulin secretion by the pancreas is impaired or is completely missing, causing high levels of blood glucose in the affected patients." (PMID 33445438, 2021). "Multiple daily injections (MDI) therapy is the most common treatment for type 1 diabetes (T1D), consisting of long-acting insulin to cover fasting conditions and rapid-acting insulin to cover meals." (PMID 35082757, 2021). "The model used in our study mimics type I diabetes, as streptozotocin leads to toxic degeneration of the insulin-producing beta cells." (PMID 34639032, 2021). "Type 1 diabetes (T1D) is an endocrine disorder in which the immune system attacks the beta cells of the pancreas, eliminating the body’s ability to produce insulin." (PMID 33407910, 2021). "Type 1 diabetes develops at early stages of life due to an auto‐immune disorder where the cells of the immune system attack the insulin producing β cells of the pancreas." (PMID 34319011, 2021). "Carbohydrate counting and carbohydrate-to-insulin ratio (CHO/IR) are a valuable tool in the management of type 1 diabetes in improving glycemic control and flexibility in eating habits." (PMID 33732212, 2021). "Free AAC2, free human insulin (hINS) and AAC2-bound-human insulin (AAC2-hINS) were tested in streptozotocin (STZ)-induced mouse model of type 1 diabetes." (PMID 35056977, 2021). "Type 1 diabetes (T1D) is an autoimmune condition characterized by insulin-producing β cell destruction involving both innate and adaptive immune cells affecting glucose metabolism." (PMID 33679757, 2021). "Type 1 diabetes (T1D) affects ~10% of the diabetic population and is characterized by the destruction of the insulin-producing beta cells in the pancreatic islets by an immune-mediated process, resulting in the disruption of proper glucose regulation." (PMID 34944640, 2021). "Few studies have systematically examined the long-term effects of insulin pumps on habitual sleep in adults with type 1 diabetes, and these have used self-report sleep assessments." (PMID 33628834, 2021). "Patients suffering type 1 diabetes depend on the appropriate estimation of the units of insulin they have to use in order to keep blood glucose levels in range (considering the calories taken and the physical exercise carried out)." (PMID 34300672, 2021). "The optimal time to bolus insulin for meals is challenging for children and adolescents with type 1 diabetes (T1D)." (PMID 34836409, 2021). "DKA is a potentially lethal condition that is more common in patients with type 1 diabetes who exhibit poor compliance or inadequate insulin replacement therapy." (PMID 34631141, 2021). "The patient was a 16-year-old female with a past medical history of type 1 diabetes on insulin pump therapy, previous episodes of DKA, and autoimmune hypothyroidism." (PMID 34437030, 2021).
type 1 diabetes (continued). "Type 1 Diabetes Mellitus (T1DM) is an autoimmune condition characterized by dysfunctions in insulin secretion from the islets of Langerhans in the pancreas." (PMID 34073433, 2021). "Type 1 diabetes mellitus (T1DM) patients adjust insulin doses in order to properly fit the carbohydrate intake to keep blood glucose levels in range." (PMID 34300672, 2021). "We have investigated the plasma levels of AG and UAG in lean and obese patients with type 1 diabetes and found that obesity in type 1 diabetes appears to be more insulin mediated than by the ghrelin system." (PMID 34294136, 2021). "The basis of type 1 diabetes (T1D) is an autoimmune inflammation leading to destruction of the β cells of the pancreatic islets that produce insulin." (PMID 34829603, 2021). "Type 1 diabetes (T1D) is characterised by the chronic immune-mediated destruction of pancreatic β-cells, with affected individuals requiring lifelong exogenous insulin." (PMID 34361954, 2021). "Glucose homeostasis-centered models, focusing on the glucose-insulin interplay, lie at the heart of mathematical models developed for type 1 diabetes, e.g., to aid insulin-pumps, and to develop a so-called artifical pancreas." (PMID 34140893, 2021). "An additional analysis of the DPV registry examined 525 youth with type 1 diabetes treated with metformin in addition to insulin compared to over 57,000 youth on insulin alone." (PMID 33828529, 2021). "Insulin’s discovery by Banting and Best at the University of Toronto (ON, Canada) in 1921 meant that type 1 diabetes went from being a death sentence to a manageable chronic condition." (PMID 33483763, 2021). "In order to assess responder status based on changes in insulin sensitivity in response to changes in PA levels, we divided individuals with type 2 and type 1 diabetes into four groups, Q1, Q2, Q3 and Q4." (PMID 34659107, 2021). "Type 1 diabetes is a chronic disease characterized by the autoimmune destruction of insulin-secreting B-cells and requires complex daily care regimens." (PMID 34281086, 2021). "Type 1 diabetes is a chronic disease characterized by autoimmune-mediated destruction of the insulin-producing β cells in the pancreas." (PMID 34882233, 2021). "Type 1 diabetes (T1D) is a chronic autoimmune condition in which the pancreas produces less insulin than required." (PMID 34977126, 2021). "Insulin injection is currently the main therapy for type 1 diabetes (T1D) or late stage of severe type 2 diabetes (T2D)." (PMID 34447354, 2021). "For example, people with type 1 diabetes often apply complex treatment regimens including multiple daily insulin doses and carbohydrate counting." (PMID 36994341, 2021). "Type I diabetes (T1D) is an autoimmune disease commonly found in children involving T-cell mediated immune destruction of the insulin-producing beta cells in the pancreas." (PMID 33763057, 2021). "Type 1 diabetes is an autoimmune disease resulting in the destruction of insulin secreting β-cells within the pancreas." (PMID 34121470, 2021). "Type 1 diabetes (T1D) is an autoimmune disease in which β cells of the pancreas are destroyed, resulting in a life-long dependence on exogenous insulin." (PMID 33351781, 2021). "The UVAPadova 2018 model is a maximal model that describes the relationship among glucose, insulin and glucagon only for patients with Type 1 diabetes." (PMID 34570804, 2021). "Future research should consider this aspect when investigating the impact of insulin therapy among employees with diabetes type 1." (PMID 34803795, 2021). "Type 1 diabetes is known as juvenile diabetes or insulin-dependent diabetes which occurs when the immune system of the body damages the insulin release cell; finally, it removes insulin production from the body." (PMID 34462631, 2021).
type 1 diabetes (continued). "Although the destruction of insulin-producing pancreatic beta cells seen in type 1 diabetes is primarily characterized by autoreactive T cells, recent studies suggest that neutrophils also play an essential role in the development of type 1 diabetes." (PMID 34394099, 2021). "Intensive glucose control with insulin has been shown to reduce microvascular and macrovascular complications in patients with type 1 diabetes." (PMID 34439553, 2021). "On the other hand, another study observed higher total plasma ghrelin concentrations in type 1 diabetes patients, which declined by 29% after insulin treatment." (PMID 34294136, 2021). "The FDA guidance indicates that “the APDS is intended for patients with type 1 diabetes for the subcutaneous infusion of insulin and the continuous measurement of interstitial glucose to aid in the management of their disease." (PMID 33679974, 2021). "Carbohydrate counting (CHC) is the established form of calculating bolus insulin for meals in children with type 1 diabetes (T1DM)." (PMID 34684559, 2021). "For women with type 1 diabetes, who lack biologically active pancreatic insulin secretion, it is particularly challenging to balance the achievement of tight pregnancy glucose targets with the risk of daily and severe hypoglycemic events." (PMID 33512267, 2021). "The main role of insulin is to reduce blood sugar; it can increase cell permeability to monosaccharides, amino acids, and fatty acids and is the best treatment for type 1 diabetes so far." (PMID 34095316, 2021). "Type 1 diabetes is a chronic, progressive disease characterised by T cell-mediated autoimmune destruction of insulin-producing pancreatic beta cells." (PMID 33145642, 2021). "Leonard Thompson was the first person to receive insulin as a treatment for type 1 diabetes in 1922 in Canada." (PMID 33483763, 2021). "Type 1 diabetes is an immune-driven disease, where the insulin-producing beta cells from the pancreatic islets of Langerhans becomes target of immune-mediated destruction." (PMID 34691048, 2021). "This insulin secretion insufficiency occurs when there is an absolute (Type 1 diabetes, T1D) or relative (Type 2 diabetes, T2D) decrease in the number of β-cells." (PMID 33239359, 2021). "Sodium-glucose cotransporter 2 (SGLT2) inhibitors are the insulin-independent, glucose-dependent antihyperglycemic agents and demonstrate some potential in the treatment of type 1 diabetes 12–15." (PMID 34394274, 2021). "Type 1 diabetes (T1D) is an autoimmune disease that results from the destruction of insulin-producing β cells." (PMID 34394099, 2021). "Patients with Type-1 diabetes (T1D) require an effective tool to monitor these levels in order to make appropriate decisions regarding insulin administration and food intake to keep BG levels in target range." (PMID 34934084, 2021). "The purpose of this study was to describe long-term changes in glycemic control and objective sleep after initiating hybrid closed loop (HCL) insulin delivery in adults with type 1 diabetes and hypoglycemia unawareness." (PMID 33628834, 2021). "Research Design and Methods: We conducted a two-center, randomized crossover trial comparing automated insulin delivery with sensor-augmented pump therapy in 36 adults with type 1 diabetes." (PMID 33050728, 2021). "The similarity also involved recently discovered autoantigens in type 1 diabetes such as a hybrid peptides of insulin and the defective ribosomal insulin gene product." (PMID 33542414, 2021). "Hypoglycemic events are probably common in diabetic patients who use insulin, and patients with type 1 diabetes (T1D) are more likely to develop hypoglycemia as compared with type 2 diabetic patients." (PMID 34690922, 2021). "Almost 1.6 million Americans have Type 1 Diabetes (T1D), an autoimmune disease that results in destruction of the insulin producing β cells in the pancreas and eventually requires exogenous insulin." (PMID 33717184, 2021).